CD4 (CD4 molecule)
Diseases named in the same sentence as CD4 in open-access papers (continued):
Sharing a sentence is not in itself a finding about the gene and the disease.
lymphedema (continued). "Knowing that the absence of CD4+ T cells prevents lymphedema, we then evaluated if adoptive transfer of naive CD4+ T cells from WT mice to CD4KO mice after lymphatic injury was sufficient to induce lymphedema." (PMID 29773802, 2018). "Leukocyte count, lymphocyte count, and CD4/CD8 ratio in CD3+ cells in peripheral blood were not significantly different among lymphedema, post-LVA, and healthy controls (HCs)." (PMID 37250774, 2023). "In a human analysis of the influence of LVA on lymphedema, LVA reduced the proportion of CD4+ T cells in lymphedematous tissue, which may be directed back into circulation in the peripheral blood." (PMID 37250774, 2023). "Studies reported that animal models with no CD4 + cells did not develop lymphedema after lymph node removal." (PMID 36571707, 2023). "In contrast to CCR7 expression in CD4+ T cells, the number of CCR7+CD8+ cells was significantly decreased, whereas that of CCR7−CD8+ cells was significantly increased in post-LVA compared with that in lymphedema." (PMID 37250774, 2023). "We examined the inflammatory cytokine production in CD4+ T cells between lymphedema and post-LVA and found that IFN-γ in CD4+PD-1+ T cells and IL-17A in CD4+ T cells were downregulated post-LVA compared with that in lymphedema, while IL-4 in CD4+ T cells was not significantly different." (PMID 37250774, 2023). "In the dermis of lymphedema patients, MCT cells have been identified as well as CD4-positive cells." (PMID 37886950, 2023). "Surprisingly though, the non-lymphedematous tissue of lymphedema patients displayed an increased CD4 expression as well." (PMID 36421681, 2022). "Surprisingly though, an increased collagen deposition and increased expression level of CD4 were also found in the non-edematous tissue from lymphedema patients, suggesting systemic changes in lymphedema patients." (PMID 36421681, 2022). "When CD4+ T cells were sequestered in the lymph node using a sphingosine-1-phosphate receptor modulator, animals did not develop lymphedema." (PMID 32268536, 2020). "T cell inflammatory responses are necessary for the development of lymphedema since nude mice (lack all T cells) or mice lacking CD4+ cells (CD4KO) do not develop lymphedema after skin and lymphatic excision." (PMID 30936872, 2019). "Using mouse models of lymphedema, we have also demonstrated that, in contrast to wild-type (WT) mice, mice lacking T cells in general (nude mice) or CD4+ T cells in particular (CD4 knockout, [CD4KO]) do not develop lymphedema after lymphatic injury." (PMID 29773802, 2018). "In this study, we confirm that non-conventional T cells such as NKT cells do not have as great of a role as traditional CD4+ T cells by demonstrating that NK1.1 depletion does not reverse lymphedema in the same way that CD4 depletion does." (PMID 29773802, 2018). "Moreover, the frequency of CD4+ and CD8+ T cells expressing IL-26 was significantly increased following filarial antigen stimulation in filarial lymphedema individuals." (PMID 24699268, 2014). "We found that depletion of CD4+ but not CD8+ or CD25+ cells resulted in marked improvements in lymphedema and decreased tail swelling, adipose tissue deposition, and fibrosis." (PMID 23185491, 2012). "In addition to innate immune modulation, studies of overt filarial infection (i.e., without manifestations of clinical lymphedema) have demonstrated reduced CD4+ T-cell activation as a result of increased dendritic cell (DC) death." (PMID 38612716, 2024). "Finally, the evaluation of the immune cell infiltrate verified the increased CD4+ cell and macrophage infiltration in lymphedema and lipedema respectively, without depicting a distinct immune cell profile in lipohypertrophy." (PMID 37108757, 2023).
lymphedema (continued). "Cytometric evaluation of cells isolated from popliteal nodes showed that, in comparison to normal lymph flow and lack of saprophyte infection, lymphedema itself and S. epidermidis infection with or without lymph stasis significantly reduced the percentage of CD4+ T helper lymphocytes and monocytes." (PMID 38137455, 2023). "Interestingly and in clear distinction to lipedema and secondary lymphedema, no increased immune cell infiltration was detected in lipohypertrophy, while the infiltration with CD4+, CD68+ or CD163+ cells was found comparable to the healthy controls." (PMID 37108757, 2023). "Surprisingly, an increased collagen deposition as well as CD4 expression were also detectable in the non-lymphedematous tissue of lymphedema patients, suggesting that lymphedema may trigger systemic changes beyond the affected extremity." (PMID 36421681, 2022). "Similarly, in our study analysing samples from chronic stages of secondary lymphedema, we found higher relative content of activated CD4+ T lymphocytes but no significant increase in the content of macrophages when compared with healthy AT." (PMID 33854130, 2021). "With evidence demonstrating that systemic DCs travel from the skin to the lymph nodes with subsequent migration of CD4+ T cells from the lymph nodes to the skin, we then hypothesized that T cell receptor (TCR) activation is critical to the development of lymphedema." (PMID 29773802, 2018). "Knowing this, we confirmed our hypothesis that CD4+ T cells must first be activated to promote lymphedema by demonstrating that the absence of the appropriate cognate antigen for the TCR or CD28 prevents the accumulation of the distinct inflammatory infiltrate seen in lymphedematous skin." (PMID 29773802, 2018). "Additionally, at the late stages of lymphedema development, the activation of lymphatic endothelial cells through lymphatic injury may induce chemokine and cytokine production, such as CCL21, to promote the infiltration and proliferation of CD4+ T cells around the lymphatic vessels." (PMID 39941140, 2025). "In support of this we found that depletion of CD4+, but not CD8 or CD25+ cells, significantly decreased tail lymphedema, inflammation, fibrosis, and adipose deposition." (PMID 23185491, 2012). "In addition, we have shown that depletion of CD4+ cells, but not CD8+ or CD25+ cells markedly decreases that pathological findings of lymphedema including swelling, fibrosis, adipose deposition, and lymphatic dysfunction." (PMID 23185491, 2012).
allergic rhinitis (54 papers, 2009 to 2025). Inflammation of the nasal mucous membranes caused by an IgE-mediated response to external allergens. "We found that the 19q13.43 locus near ZNF776 was associated with allergic rhinitis (GWAS P value 5.0 × 10−8) as well as CD4+ gene expression (χ2 = 19.55, FDR-adjusted P value 0.00078)." (PMID 25085501, 2014). "Flow cytometry analysis revealed that Rh1 significantly curbed the rise in IL-4+ CD4+ cells in allergic rhinitis mice while elevating IFN-γ+ CD4+ cell proportions, demonstrating restoration of Th1/Th2 immune balance." (PMID 41155644, 2025). "Allergic rhinitis (AR), a globally prevalent allergic airway disorder, fundamentally involves CD4+T cell subset imbalance, notably T helper 2 (Th2) hyperpolarization." (PMID 41246337, 2025). "In individuals with allergic rhinitis, mature DCs interact with CD4+ Th2 cells, increasing IgE production and eosinophilic inflammation in nasal tissue." (PMID 41200280, 2025). "In allergic rhinitis models, Rh1 administration significantly decreased IL-4-positive CD4+ T cells while increasing IFN-γ-positive CD4+ T cells in nasal-associated lymphoid tissue." (PMID 41155644, 2025). "The last allergic rhinitis study showed that human mesenchymal stem cells (HMSC)-EVs co-cultured with CD4+ T cells inhibited the Th2 differentiation by regulating the miR-146a-5p/SERPINB2 pathway." (PMID 38674077, 2024). "MSCs and IL-10-MSCs were co-cultured with CD4+ T cells from patients with allergic rhinitis (AR), and the levels of Th2 cells and corresponding type 2 cytokines were studied." (PMID 38093354, 2023). "For example, the numbers of CD45RO+ memory CD4 T cells in the nasal mucosa of patients with seasonal allergic rhinitis increased during continuous exposure to allergens during the pollen season compared to the non-pollen season." (PMID 36591273, 2022). "sEV‐mDCs were co‐cultured with isolated CD4+T cells or peripheral blood mononuclear cells (PBMCs) from patients with allergic rhinitis." (PMID 35415925, 2022). "Exposure to PM2.5 exacerbates allergic rhinitis in mice by increasing DNA methylation of the interferon-gamma gene promoter in CD4+ T cells via the extracellular signal-regulated kinase-DNA methyltransferase pathway." (PMID 35378908, 2022). "Our findings indicated that low dose VD3 supply in pregnant mice's diet suppressed Th2 and Th17 responses in allergic rhinitis by elevating the Th1 subtype and the proportion of CD4+CD25+FoxP3+Tregs in offspring." (PMID 33954205, 2021). "A recent study in CD4+ T-cells demonstrated that miR-155 expression was altered in response to allergic stimuli or glucocorticoid treatment in a set of dust-mite allergic rhinitis, healthy, and asthmatic subjects." (PMID 32381094, 2020). "Targeting the CD40/CD40 ligand (CD154) interaction by CD40 siRNA given to bone-marrow-derived DCs attenuated allergic rhinitis and induced the conversion of CD4+ T cells into regulatory T cells." (PMID 31991941, 2020). "A recent study showed that LGG in addition to vitamin D supplementation increased the number of CD4+CD25+FoxP3+ Treg in children with allergic rhinitis." (PMID 27525046, 2016). "Immunocytochemical analysis of nasal mucosa of patients suffering from seasonal allergic rhinitis revealed an increase in CD4+ CD45RO+ cells during pollen season." (PMID 27799958, 2016). "A recent study demonstrated an increased number of effector/memory T cells (CD4+CD25low) in patients with seasonal allergic rhinitis 6 h after nasal allergen challenge with grass pollen." (PMID 27799958, 2016). "The inducible IL-10+ Mos showed an immune suppressor effect on the activities of CD4+ effector T cells and the Th2 polarization in a mouse model of allergic rhinitis." (PMID 26526003, 2015). "The higher levels of IL-17 producing CD3+CD4+T cells in peripheral blood of polysensitized allergic rhinitis patients were demonstrated." (PMID 24428928, 2014).
allergic rhinitis (continued). "Gene expression microarray analysis was performed to profile gene expression in diluent- (D), allergen- (A), and allergen + hydrocortisone- (T) challenged CD4+ T cells from patients with seasonal allergic rhinitis." (PMID 22701743, 2012). "We proceeded by examining the TCR pathway in allergen-challenged CD4+ cells from patients with seasonal allergic rhinitis (SAR)." (PMID 19216740, 2009). "We proceeded to study the TCR pathway genes in CD4+ cells from patients with seasonal allergic rhinitis (SAR)." (PMID 19216740, 2009). "It has been reported that the relative abundance of CD4+CD25+Foxp3+ Tregs was decreased significantly in a Guinea pig model of allergic rhinitis and that increasing the percentage of CD4+CD25+Foxp3+ Tregs restrains allergic reactions through an increase in IL-10 production." (PMID 34147127, 2021). "Our results indicate that oral administration of LFK may alleviate nasal symptoms, reduce nasal eosinophilia, and increase the percentage of CD4+CD25+ Tregs in experimental allergic rhinitis." (PMID 23554753, 2012). "Relevant studies have proved that oral bifidobacteria intervention in early life can effectively inhibit the symptoms of allergic rhinitis in mice later in life, which could be attributed to the inhibition of Th2 cell response and enhancement of the function of CD4+CD25+Treg cells." (PMID 39243698, 2024). "However, the role of TRPV1 in CD4+ T cell in allergic rhinitis remains poorly understood." (PMID 26700618, 2016). "CD4+ lymphocytes with a Th2 phenotype may play some important roles in the development of allergic rhinitis, and the suppression of Th2 lymphocytes could have the potential to be new therapeutic targets for the treatment of allergic rhinitis." (PMID 22164170, 2011). "In the case of allergic rhinitis, the expression of IL17RB on CD4 T cells also increased in the blood of patients with seasonal allergic rhinitis after exposure to natural allergens." (PMID 36591273, 2022). "Adoptive transfer CD4+CD25+FoxP3+Tregs of VD3 supplementation groups promoted Th1 and suppressed Th2 responses in the offspring during allergic rhinitis." (PMID 33954205, 2021). "However, it remains unclear whether CD4+CD25+ TRegs are involved in allergic rhinitis (AR)." (PMID 31826046, 2018). "Immunohistochemistry testing of the nasal mucosa of two HTLV-1 carriers with non-allergic rhinitis was positive for T-cell markers CD45RO and CD4, with diffuse and focal distribution respectively." (PMID 22499368, 2012). "Until now, the expression and functional role of TRPV1 in immune cells including CD4+ T cells had not been investigated in allergic rhinitis (AR)." (PMID 26700618, 2016). "SST may also suppress IL-4 production in CD4+ T cells by influencing CD28-CD86 interactions and may correct a Th2-dominant condition in allergic rhinitis." (PMID 24324897, 2013). "However, in our unpublished study, we have investigated the dose-response relationship of B. breve on a murine allergic rhinitis model, presenting results of decreased IL–4 and OVA-specific IgE levels and increased CD4+CD25+ Tregs in the spleen at a dose of 109CFU.B." (PMID 26445348, 2015). "In a previous histological study, AR demonstrated a selective increase in CD4+ T cells, CD3+ T cells, B cells, and γδ T cells in the nasal mucosa and increased levels of eosinophils and mast cells within the submucosa, independent of levels in peripheral blood, compared with non-allergic rhinitis." (PMID 26376485, 2015). "Thereafter, to determine the involvement of Tregs, we first examined the distribution and function of CD4+CD25+ Tregs, the representative population of immunosuppressive regulatory cells in the suppression of Th2-mediated allergic responses in sublingually treated mice with allergic rhinitis." (PMID 23118775, 2012).
chronic GVHD (54 papers, 2006 to 2025). "Consistently, in a chronic GVHD model with DBA/2 donors and BALB/c recipients, loss of CD4+ Treg cells was associated with chronic GVHD onset, and infusion of donor-type Treg cells prevented the disease onset or ameliorated the progression of chronic GVHD." (PMID 34539630, 2021). "Chronic GVHD is an autoimmune-like syndrome caused by the interactions of donor CD4+ T and B cells and production of IgG2, 5–9." (PMID 29042531, 2017). "On the other hand, prevalence of chronic GVHD is characterized by constitutive phosphorylation of Stat5 in conventional CD4+ T cells (Tcons) associated with elevated amounts of IL-7 and IL-15 and relative functional deficiency of IL-2." (PMID 28819653, 2017). "A recent study that analyzed CD4+Treg heterogeneity with a large panel of functional markers using mass cytometry by time of flight revealed that in addition to the numerical deficiency, reduced heterogeneity of CD4+Tregs was associated with the development of chronic GVHD." (PMID 34526990, 2021). "Chronic graft-versus-host disease (cGVHD) is an autoimmune-like syndrome mediated by pathogenic CD4+ T and B cells, but the function of extrafollicular and germinal center CD4+ T and B interactions in cGVHD pathogenesis remains largely unknown." (PMID 29042531, 2017). "Rivas and colleagues demonstrated in a murine model that NK cells can control the proliferation of antigen-activated CD4 + T cells, leading to reduced chronic GvHD, potentially through NKG2D receptor-ligand interactions." (PMID 41194247, 2025). "Chronic GVHD and its therapies further impair CD4+ recovery, with thymic damage leading to prolonged deficits in naive T-cell production." (PMID 41012135, 2025). "Chronic graft-versus-host disease (cGVHD) arose from the alloreactive activation of donor CD4+ T cells by recipient antigen-presenting cells (APCs), resulting in SLE-like manifestations." (PMID 41373904, 2025). "To investigate the impact of DDIT3 on the development of SLE, we conducted a chronic graft-versus-host disease (cGVHD) lupus-like model by transferring CD4+ T cells from Bm12 mice into WT and KO mice." (PMID 40166629, 2025). "In the research conducted by K. Jimbo and colleagues, it was observed that there was a significant increase in CD4+ Tscm (T stem cells) in patients with chronic graft-versus-host disease (cGVHD) following allogeneic hematopoietic cell transplantation." (PMID 39035005, 2024). "Sex differences in chronic GVHD were more widespread; females exhibited significantly greater numbers of total splenocytes and host CD4 Tfh cells, B cells and CD8 T cells consistent with reports of greater female autoantibody production in this model." (PMID 38915570, 2024). "We also observed more circulating CD4+CD70+ T cells in patients with chronic GVHD (median onset 210 days after transplant)." (PMID 39028952, 2024). "As depicted in the diagram, we propose how donor CD4+ T cells mediate autoimmune-like chronic GVHD pathogenesis." (PMID 34539630, 2021). "Targeting autoreactive CD4+ Trm cells in the GVHD target tissues for treatment of chronic GVHD is under investigation." (PMID 34539630, 2021). "In chronic GVHD, inflammation is mediated by alloreactive CD4+ T cells, B‐cell activation, and generalized fibrosis/sclerosis perpetrated by macrophages." (PMID 33058566, 2021). "Autoreactive CD4+ T cells in chronic GVHD recipients include those derived from the mature T cells in the graft or those from de novo-generation in the damaged thymus." (PMID 34539630, 2021). "This association between response to mRNA vaccine and naive CD4+ T-cell counts suggests a share mechanisms for poor responses to the vaccine in aged and in allo-HCT (and particularly those with chronic GVHD) patients." (PMID 34689821, 2021).